TAS2R6P (taste 2 receptor member 6, pseudogene)
Synonyms: T2R06; T2R6; PS3; TAS2R6
Gene: Processed pseudogene on chromosome 7 (141,787,815 to 141,788,640, forward strand). Ensembl gene ENSG00000270923.
Diseases named in the same sentence as TAS2R6P in open-access papers:
TAS2R6P is named in the same sentence as 6 diseases in open-access papers, as found by Europe PMC text mining. Sharing a sentence is not in itself a finding about the gene and the disease.
TAS2R6P shares sentences with these, for which no sentence is quoted: autosomal recessive disease (1 paper); breast carcinoma (1); cancer (1); deafness (1); infection (1); virus infection (1).